IGHJ6 (immunoglobulin heavy joining 6)
Synonyms: JH6b
Gene: Immunoglobulin joining (J) gene on chromosome 14 (105,863,198 to 105,863,258, reverse strand). Ensembl gene ENSG00000211900.
Diseases named in the same sentence as IGHJ6 in open-access papers:
IGHJ6 is named in the same sentence as 2 diseases in open-access papers, as found by Europe PMC text mining. Sharing a sentence is not in itself a finding about the gene and the disease. The quoted sentences say what the papers report.
COVID-19 (4 papers, 2021 to 2024). A disease caused by infection with severe acute respiratory syndrome coronavirus 2. "We found a preferential usage of IGHV3-9, IGHV3-30, IGHV3-43, IGHV4-31, and IGHJ6 germ line genes in COVID-19 patients." (PMID 34878902, 2022). "Similarly, in COVID-19 patients, observed a pronounced skewing toward specific V gene segments, particularly IgHV4-4 in conjunction with IgHJ6, within clonal B cell receptors." (PMID 39902045, 2024). "Furthermore, 17 IGHV genes combined with IGHJ6 increased in COVID-19 samples, highlighting the critical role of IGHJ6 in the SARS-COV-2-elicited antibody responses." (PMID 34878902, 2022).
IGHJ6 also shares sentences with these, for which no sentence is quoted: infection (1 paper).